IGF2BP3 (insulin like growth factor 2 mRNA binding protein 3)
Diseases named in the same sentence as IGF2BP3 in open-access papers (continued):
Sharing a sentence is not in itself a finding about the gene and the disease.
Salmonella Infections (1 paper, 2020). Infections with bacteria of the genus SALMONELLA. "Finally, the GO and KEGG analyses of biologically enriched genes that were positively correlated with IGF2BP2 and IGF2BP3 expression revealed the top 10 relevant biological processes, including cell junction organization, salmonella infection, mitotic nuclear division, and cell cycle." (PMID 33246429, 2020).
skin cancer (1 paper, 2025). "BRD4 expression, like IGF2BP3, was higher in tumor metastases than in primary tumors or normal tissues in both the TCGA pan-cancer and TNM skin cancer cohorts." (PMID 40162116, 2025).
sterility (1 paper, 2026). "Furthermore, adult Igf2bp3−/− males exhibited sub-fertility or even sterility, with testes approximately half the size of those in Igf2bp3+/+ (wild-type, WT) and Igf2bp3+/− mice." (PMID 41350940, 2026).
testicular cancer (1 paper, 2018). A primary or metastatic malignant neoplasm that affects the testis. "While IGF2BP1 was detected in all carcinomas, IGF2BP2 and IGF2BP3 were only seen in a subset of testicular cancers." (PMID 29736175, 2018).
thyroid (1 paper, 2016). "TCF12, KDM5C, IGF2BP3 and MAP4K3 mutations newly identified in our study might possibly be follicular tumor-specific thyroid mutations." (PMID 27626165, 2016).
upper tract urothelial carcinoma (1 paper, 2020). "In upper tract urothelial carcinoma, patients with up-regulated IGF2BP3 presented significantly poorer RFS, cancer-specific survival and overall survival." (PMID 32710725, 2020).
Ureteral obstruction (1 paper, 2023). Obstruction of the flow of urine through the ureter. "We first assessed the expression of IGF2BP3 in various well-established animal models of CKD induced by unilateral ureteral obstruction (UUO), ischemia/reperfusion injury (IRI), adriamycin (ADR), and angiotensin II (Ang II), respectively." (PMID 36520532, 2023).
urothelial carcinoma (1 paper, 2024). A malignant neoplasm derived from the transitional epithelium of the urinary tract (urinary bladder, ureter, urethra, or renal pelvis). "The expression of IGF2BP3 is related to disease recurrence and cancer-specific mortality in urothelial carcinoma, which could improve risk stratification of urothelial carcinoma patients undergoing radical nephroureterectomy." (PMID 39680264, 2024).
uterine carcinosarcoma (1 paper, 2023). A usually aggressive malignant neoplasm arising from the uterine corpus and less often the cervix. "Among all cancers tested, the IGF2BP3 gene was amplified in multiple types of cancer, with the highest alteration frequency (>6%) in uterine carcinosarcoma (UCS)." (PMID 36761737, 2023).
vascular tumors (1 paper, 2020). "IGF2BP3 might also be correlated with the pathogenesis of vascular tumors via CD44 mRNA stabilization and translation." (PMID 32293476, 2020).
virus infection (1 paper, 2024). "As multiple pathways enriched by IGF2BP3 overexpression are related to virus infection, we conducted KEGG analysis of the mRNA-seq data and found that herpes simplex virus infection was the top enriched pathway." (PMID 38167409, 2024).
ZIKV) infection (1 paper, 2024). "Zika virus (ZIKV) infection does not significantly impact the association of IGF2BP2 with IGF2BP1, IGF2BP3, and YBX1." (PMID 39565347, 2024).
tumor (278 papers, 2008 to 2026). "We found that CENPA and IGF2BP3 were most closely associated with prognosis and tumor immunity in KIRC, so we explored the function and mechanism of CENPA and IGF2BP3 in KIRC." (PMID 41589308, 2025). "Previous studies have suggested that IGF2BP3 is overexpressed in various malignant tumors and is associated with tumor progression, metastasis, and poor prognosis." (PMID 40672753, 2025). "Our results show that high levels of IGF2BP3 are linked to higher tumor grade, ER negativity, PR negativity, HER2 negativity, higher Ki-67 index, and the TNBC molecular subtype." (PMID 40672753, 2025). "In another study of 118 TNBC patients, positive IGF2BP3 expression was linked to larger tumor size, higher clinical stage, and basal morphology." (PMID 40672753, 2025). "Difference and correlation analyses revealed that two types of tumor-infiltrating immune cells (TICs) were significantly associated with IGF2BP3 expression." (PMID 40801655, 2025). "The expression level of IGF2BP3 was significantly associated with multiple GC characteristics, including lymph node involvement (p = 0.016) and tumor-node-metastasis (TNM) staging (p = 0.028)." (PMID 40847370, 2025). "We revealed the expression of IGF2BP3 in CC exceeded adjacent tissues, and was positively associated with tumor stage using human CC tissue microarrays." (PMID 38355626, 2024). "Together, these results expand our understanding of the cancer-associated function of lncRNAs, highlighting the ZNF674-AS1/IGF2BP3/CA9 axis as a constituting regulatory mode in NB tumor growth and cisplatin resistance." (PMID 38177154, 2024). "IGF2BP3 is a highly conserved gene with few mutations, and its stability is favourable for its use as a tumour marker." (PMID 38358034, 2024). "N6-methyladenosine (m6A) and its associated reader protein insulin like growth factor 2 mRNA binding protein 3 (IGF2BP3) are involved in tumor initiation and progression via regulating RNA metabolism." (PMID 38448411, 2024). "More importantly, IGF2BP3 was closely associated with the following five signaling pathways (r > 0.4), that were tumor proliferation signature, G2M checkpoint, PI3K_AKT_mTOR_pathway, MYC targets, and DNA repair related pathways." (PMID 38577615, 2024). "Among the top upregulated lactylated proteins was IGF2BP3, a critical m6A reader implicated in tumor progression and therapeutic resistance." (PMID 39450426, 2024). "To investigate the functional association of the IGF2BP3/MIB1/FTO loop with IGF2BP3-induced NETosis and tumor survival, we disrupted the pathway using a genetic approach." (PMID 38167409, 2024). "The aberrantly high expression of IGF2BP3 can preferentially detect m6A-modified target RNAs, thereby facilitating target RNA stability and expression, causing tumor progression, angiogenesis, glycolysis, and chemoresistance." (PMID 37897508, 2024). "IGF2BP3 is an RNA-binding protein that has recently been implicated in oncogenesis and tumor progression among various cancers." (PMID 37760460, 2023). "The elevated expression of IGF2BP3 was also significantly associated with certain clinicopathological features such as Tumor Node Metastasis (TNM) staging and Dukes staging." (PMID 37658049, 2023). "Third, this study provides a foundation for further studies of the correlation between IGF2BP3 and the tumor-associated immune microenvironment." (PMID 36732736, 2023). "As an RNA-binding protein associated with the PI3K pathway, IGF2BP3 can function as a m6a reader to engage in tumor m6a modification." (PMID 36450891, 2023). "Existing studies have shown that IGF2BP3 expression is abnormally elevated in a variety of cancers and is positively associated with tumor malignancy." (PMID 37340423, 2023). "In contrast, cell migration was oppositely regulated when IGF2BP3-deprived cells received EVs from parental, IGF2BP3-positive cells, indicating that IGF2BP3-associated alterations of EVs influence the tumor phenotype and spreading capacity of EWS." (PMID 37353558, 2023).
tumor (continued). "IGF2BP3 mutation resulted in a significant tumour suppression when compared with wild‐type IGF2BP3 group." (PMID 37877353, 2023). "Among these, IGF2BP3 has been implicated in various aspects of human tumor progression regulating cell growth, migration, and response to drugs." (PMID 37658049, 2023). "Given the facts that circITGB6 promotes EMT process and cell migration through its association with IGF2BP3, with limited effect on IGF2BP3 abundance, we wondered if circITGB6 promotes tumor metastasis through modulating certain mRNA cargos of IGF2BP3." (PMID 37898647, 2023). "In parallel with this study, a pancancer analysis of 9652 tumor patients in the TCGA cohort showed that high expression of IGF2BP3 was strongly associated with poor prognosis (P < 0.001)." (PMID 35217832, 2022). "circNEIL3 is packaged into exosomes and then transmitted to tumor associated macrophages (TAMs) that enable them to acquire immunosuppressive effect by stabilizing IGF2BP3, and promoting glioma progression." (PMID 35541906, 2022). "In oral cancer patients, IGF2BP3 expression was significantly associated with overall survival (P = 0.038) based on tumor location." (PMID 36237306, 2022). "In previous studies of ccRCC, IGF2BP3 has been shown to be associated with poor tumor prognosis and metastasis." (PMID 36338999, 2022). "The results showed that high IGF2BP3 expression was associated with advanced clinical stages of EC, high tumor grade, vascular invasion, and distant metastasis." (PMID 35676262, 2022). "Our results indicated that IGF2BP3 mRNA expression level (p = 0.006), lymph node stage (p < 0.001), metastasis stage (p = 0.008), and tumor stage (p < 0.001) were significantly associated with the OS of patients with SCLC." (PMID 35845940, 2022). "Recent studies have shown that IGF2BP family members, including IGF2BP3, act as posttranscriptional regulatory factors of gene expression, which are associated with tumor cell proliferation, survival, chemotherapy resistance, and invasion." (PMID 35845940, 2022). "IGF2BP3 plays an oncogenic role in the tumorigenesis of certain tumors and is associated with tumor progression." (PMID 35986300, 2022). "Whereas, IGF2BP3 expression was associated with various immune molecular markers involving M2 Macrophage, indicating its role in regulating tumor immunity." (PMID 34446007, 2021). "Univariate Cox regression analysis confirmed that higher IGF2BP3 expression (P < .001), T classification (P < .001) and tumour grade (P = 0.002) were associated with an increased risk of death." (PMID 33094561, 2020). "Overexpression of IGF2BP3 was observed to be significantly associated with T classification (P = 0.026) and tumour grade (P = 0.001)." (PMID 33094561, 2020). "An increase in IGF2BP3 expression is associated with increased cell invasiveness and greater dynamics of the tumor process IGF2BP2, in turn, stabilizes IGF-2 mRNA, which increases its expression contributing to tumor development." (PMID 32850012, 2020). "IGF2BP3 has been implicated in various aspects of human tumor progression regulating cell growth, migration, and the response to drugs." (PMID 32010687, 2019). "A putative role of IGF2BP3 in self-renewal and tumor initiation, i.e., two properties associated with CSCs, has been suggested in several tumors through different mechanisms." (PMID 32010687, 2019). "According to a study with microarray assays of 8,877 human cancers and normal tissues, IGF2BP3 is associated with aggressive tumor features and unfavorable outcomes." (PMID 32083017, 2019). "The expression of IGF2BP3 is strongly associated with advanced tumor stage and is a predictor of poor prognosis among patients with HCC as well as IGF2BP1." (PMID 26327240, 2015). "Spatial transcriptomic analysis demonstrates that IGF2BP3 expression is concentrated in the infiltrating front and perivascular regions, which may facilitate local tumor cell invasion and dissemination and is associated with a poor prognosis." (PMID 40867324, 2025).
tumor (continued). "Additionally, high IGF2BP3 expression was linked to advanced tumor stage, increased cell proliferation, and immune escape through modulation of the tumor immune microenvironment." (PMID 40801655, 2025). "However, IGF2BP3 displays unusually elevated expression in several cancers, including cervical, gastric, breast, and colorectal, and is closely linked to tumor aggressiveness, metastasis, and unfavorable prognosis." (PMID 40801655, 2025). "Furthermore, we noticed a significant positive association between IGF2BP3 mRNA levels and its copy number across 23 different tumor types in TCGA datasets." (PMID 38504159, 2024). "Additionally, we investigated the potential relationship between IGF2BP3 mRNA expression level and clinicopathologic characteristics, tumor mutation burden (TMB), microsatellite instability (MSI), and infiltrating immune cells in pan-cancer." (PMID 36761737, 2023). "Moreover, high IGF2BP3 expression was associated with advanced tumor-node-metastasis (TNM) stage (P = 0.037), advanced N stage (P = 0.005), tumor metastasis (P = 0.001) and patient death (P = 0.008)." (PMID 37853162, 2023). "Remarkably, several of these target genes were down-regulated following miR-Combo treatment, and have been shown to be involved in GBM progression (RAP2A), angiogenesis (SPON2), migration (CXCR4), and are associated with an increase in tumor grade (IGF2BP3, SERPINH1)." (PMID 37749143, 2023). "Although increasing lines of evidence have proved that the deviant expression of m6A modification may be the cause of tumor progression, the mechanism through which m6A regulators, especially IGF2BP3, function in NPC tumorigenesis remains unknown." (PMID 35136045, 2022). "In addition, the m6A regulator IGF2BP3 was associated with reduced cell apoptosis, larger tumor sizes, higher grade, higher clinical stage, necrosis, and CK5/6 expression and further worsened the DFS and OS of BC patients." (PMID 33926554, 2021). "IGF2BP3, one of the bona fide oncofetal proteins, serves as a post‐transcriptional fine‐tuner in various human cancers, and regulates the expression of genes implicated in the modulation of tumour cell proliferation, metastasis, survival and chemo‐resistance." (PMID 32961012, 2020). "The impact of IGF2BP3 on tumor predisposition is still obscure." (PMID 32010687, 2019). "Indeed, IGF2BP3 was shown to promote the association between the RNA-induced silencing complex with specific transcripts, and influence tumor-associated RNA regulation by modulating miRNA-mRNA interactions." (PMID 29088808, 2017). "A recent report shows that miRNA-142-5p could regulate the expression of IGF2BP3, which is strongly associated with an advanced tumor stage and is a predictor of poor prognosis among patients with HCC, as with IGF2BP1." (PMID 28302149, 2017). "GSEA analysis indicated that high IGF2BP3 expression correlated with cell cycle pathway enrichment, whereas low expression was linked to metabolic pathways, suggesting that it may influence tumor progression by regulating cell cycle and metabolic reprogramming." (PMID 40801655, 2025). "In addition to modulating tumor-intrinsic factors, IGF2BP3 has been implicated in the immunomodulation of the tumor microenvironment, from the upregulation of immune checkpoint inhibitors to the polarization of tumor-associated macrophages (TAMs) towards an immunosuppressive phenotype." (PMID 37760460, 2023). "Increased gene expression of HOXB7, KIF2C, NEK2, FOXM1 and IGF2BP3 has also been reported for several other types of cancer, suggesting that these genes may be associated with tumor growth in general." (PMID 22879911, 2012). "Consistently, there was a significantly positive correlation between the expression levels of CDK6 and IGF2BP3 in the IHC analysis of xenograft tumor model." (PMID 40083693, 2025).
tumor (continued). "Given the reported impact of IGF2BP3 on cell apoptosis and viability in other tumor types, we examined these functional phenotypes in WaGa and MKL1 cells using Annexin V, WST-1, and trypan blue assays." (PMID 40162116, 2025). "IGF2BP3, as an m6A reader, plays a dual role in tumor immunity by regulating the stability of specific mRNAs." (PMID 41589308, 2025). "The results indicate that IGF2BP3 expression was an important factor influencing tumor-specific survival." (PMID 40801655, 2025). "Insulin-like growth factor 2 mRNA-binding protein 3(IGF2BP3) is an RNA-binding protein that promotes tumor progression through its binding to non-coding RNAs." (PMID 41169378, 2025). "Previous studies have expressed that m6A and IGF2BP3 play important roles in regulating the tumor microenvironment and response to immune checkpoint drugs." (PMID 41285728, 2025). "Subsequently, we mapped the IGF2BP3 expression in various cellular subpopulations found that IGF2BP3 was expressed predominantly in tumor cells compared to other cell groups." (PMID 41285728, 2025). "WB and QRT-PCR results showed that IGF2BP3 exhibited significantly higher expression at both protein and mRNA levels in all four tumor types compared to their corresponding normal tissues." (PMID 40765570, 2025). "Consistent with our in vitro findings, knockdown of IGF2BP3 significantly suppressed xenograft growth in nude mice, which was demonstrated by a decrease in both tumor volume and tumor weight." (PMID 40530014, 2025). "Gene set enrichment analysis indicated that elevated IGF2BP3 expression was significantly linked to the cell cycle pathway, while low expression was associated with the metabolic pathway, suggesting that it may affect tumor progression by regulating the cell cycle and metabolism." (PMID 40801655, 2025). "IGF2BP3 enhances the stability of m6A-modified circCCAR1, thus accelerating tumor progression and immune evasion in hepatocellular carcinoma patients." (PMID 40770637, 2025). "As an RNA-binding protein, IGF2BP3 critically controls tumor invasiveness and metastasis by regulating the stability and translation of multiple oncogenic transcripts, such as HMGA2, E2F3, and EGFR." (PMID 40162116, 2025). "Beyond influencing growth and chemoresistance, IGF2BP3 also enhances the invasive capacity of tumor cells in vitro 20-22." (PMID 40765570, 2025). "The results showed that compared with the control group (NC+NS), the tumor volume and weight of the IGF2BP3 overexpression group (IGF2BP3+NS) were significantly increased." (PMID 40083693, 2025). "The results showed that the IGF2BP3 expression level was higher in tumor samples than in the matched peri-tumors." (PMID 40770637, 2025). "In vivo experiments conducted on nude mouse models further confirmed the role of IGF2BP3 in promoting tumor growth and conferring resistance to cisplatin." (PMID 40083693, 2025). "Insulin-like growth factor 2 mRNA-binding protein 3 (IGF2BP3) has been shown to promote cancer progression across various tumor types." (PMID 39883704, 2025). "To understand the role of IGF2BP3 in tumor progression, we studied its impact on cell migration and invasion using 2 adherent MCC cell lines, MCC26 and MCC13." (PMID 40162116, 2025). "Then, we assessed the in vivo effects of IGF2BP3 knockdown on tumor progression via the application of a xenograft model." (PMID 40530014, 2025). "The detailed mechanisms by which IGF2BP3 drives MCC tumor progression warrant further investigation." (PMID 40162116, 2025). "In our study, rescue experiments demonstrated that IGF2BP3 restoration reversed the tumor-suppressive effects of LINC01559 knockdown, confirming its functional indispensability in this axis." (PMID 40313617, 2025). "Next, we investigated IGF2BP3′s role in the tumor immune microenvironment by comparing high- and low-expression groups using GSEA." (PMID 40801655, 2025).